SRSF1 (serine and arginine rich splicing factor 1)
Diseases named in the same sentence as SRSF1 in open-access papers (continued):
Sharing a sentence is not in itself a finding about the gene and the disease.
tumor (continued). "In hepatocellular xenografts, however, SRSF1-NRS1 protein had a much lower effect on tumor formation than SRSF1." (PMID 26273603, 2015). "Together, this indicates that SRSF1 overexpression is in general the consequence of other preceding tumor-initiating genetic changes but contributes to further tumor progression." (PMID 26273603, 2015). "Though the number of samples available with matched normal controls was small, the elevated SRSF1 expression in tumor samples correlated with our finding that overexpression of SRSF1 induces MDM2-ALT1." (PMID 25845590, 2015). "This occurs during embryogenesis but also in adult fibroblasts during tissue repair, tumor progression, and inflammation when expression levels of SRSF1 increase." (PMID 26273603, 2015). "Overexpression of SRSF1 has been reported in various tumors types and this has consequences for the alternative splicing profile expressed in tumor cells." (PMID 26273603, 2015). "SRSF1 is a reported proto-oncogene and involved in mammary epithelial transformation via its overexpression and by splicing regulation of Bcl-2 family tumor suppressors." (PMID 25029565, 2014). "Tumour formation by these transformed fibroblasts is directly dependent on SRSF1 expression, since it is blocked by parallel shRNA inhibition of SRSF1." (PMID 23935626, 2013). "SRSF1 was able to promote Survivin protein translation in an mTOR-dependent manner, and was correlated with Survivin expression in tumour samples." (PMID 23592547, 2013). "Mouse COMMA1-D mammary epithelial cells form tumours more efficiently in mice after transduction with SRSF1, and transduction of MF10A cells with SRSF1 results in increased acinar size and decreased apoptosis in a 3D culture model." (PMID 23935626, 2013). "Protein expression analysis using a highly specific monoclonal antibody showed that a number of tumours have increased SRSF1 protein compared to normal tissue." (PMID 23935626, 2013). "Collectively, these results confirmed that RBM15 promoted tumor growth by mediating SRSF1." (PMID 40923717, 2026). "Through comprehensive multiomics analysis, we first revealed that SRSF1-positive malignant epithelial cells possess a unique coexpression network and exhibit significantly enhanced interactions with fibroblasts, reshaping the tumor microenvironment (TME)." (PMID 42293332, 2026). "Additionally, in vivo studies further validated that RBM15 facilitated tumor growth by regulating SRSF1." (PMID 40923717, 2026). "Because of this, SRSF1 could be a strong candidate for use in early diagnosis and predicting how a tumor will behave." (PMID 41514860, 2025). "Notably, SRSF1 inhibition in either tumor cells or CD8+T cells yield significant benefits for T cell-mediated tumor immunity." (PMID 39837814, 2025). "In summary, TN2008 effectively inhibits SRSF1, reducing tumor cell growth." (PMID 39837814, 2025). "Given the dual role of SRSF1 on tumor and T cells, we selected the significant candidate inhibitors screening by cytotoxicity assays in vitro and added into CD8+T cells at single dose (100 μM), we found that only TN2008, T4613 and T2987 have more effects on upregulation of CD8 + T cell." (PMID 39837814, 2025). "We next investigated whether SRSF1 within tumor cells could directly undermine T cells’ cytotoxic functions when recognizing tumors in response to TCRs." (PMID 39837814, 2025). "Why do T cells react so differently to SRSF1 suppression than do tumor cells?" (PMID 39837814, 2025). "SRSF1, a trans-acting factor that regulates AS, also influences tumor behavior in OS." (PMID 41268214, 2025). "The opposite effects triggered by SRSF1 in tumor or CD8 T cells may be explained by the differences from specific cell-type characteristics." (PMID 39837814, 2025).
tumor (continued). "Notably, the genes differentially expressed due to SRSF1 gene inactivation showed minimal overlap between tumor cells and T cells." (PMID 39837814, 2025). "Upon depletion of CD8 + T cells, tumor growth was delayed in SRSF1-sh group." (PMID 39837814, 2025). "Although the protumoral function of SRSF1 is well-established, the effects of inhibiting tumor-intrinsic SRSF1 on the tumor microenvironment and its impact on CD8+ T cell-mediated antitumor immunity remain unclear." (PMID 39837814, 2025). "However, the expression of mTOR was reduced while PTEN increased when SRSF1 was downregulated in tumor cells." (PMID 39837814, 2025). "Aberrant expression of SRSF1 has been reported in various types of tumors, leading to abnormal RNA splicing, which in turn promotes the proliferation, migration and apoptosis resistance of tumor cells." (PMID 39578852, 2024). "Similarly, analyses of tumor cells pointed out the altered methylation of splicing factors SRSF1 and SRSF2 in their arginine residues." (PMID 36983760, 2023). "To determine the correlation between SRSF1 expression and tumor-infiltrating immune cells, we found that the expression level of SRSF1 was positively correlated with Tr1, Th2, and central memory T cells and negatively correlated with macrophage cells (all p < 0.05)." (PMID 37206090, 2023). "NOTCH2NL, MYBL2, and UBE2T were reported to be involved in tumorigenesis, while CXCR4 and IL18R1 were associated with immune response and pathway activation, indicating SRSF1 may take part in MM progression via tumor-related pathways." (PMID 37206090, 2023). "Knockdown of SRSF1 suppresses SUMO modification of splicing factors as well as tumor progression." (PMID 36911524, 2023). "Taken together, these data suggested that SRSF1 was related to tumor immune infiltrating cells and may have participated in tumor immune escape in MM." (PMID 37206090, 2023). "In vivo, ectopic SRSF1 decoy oligonucleotide expression reduced murine tumor volume." (PMID 37510283, 2023). "Altogether, our findings showed that the SRSF1 expression level could affect tumor immune characteristics via infiltrating immune cells, TME, checkpoint markers, and immune-related genes, thereby determining the prognosis of patients with MM." (PMID 37206090, 2023). "For example, SRSF1 was found to be upregulated in many tumor cells." (PMID 36983760, 2023). "Additionally, overall number and percentage of invasive tumours per mouse and the presence of extensive collagen deposition was significantly reduced in Srsf1 depleted mice." (PMID 35589755, 2022). "Upregulation of SRSF1 activates the Wnt pathway, promoting tumor growth, which may be related to the accumulation of β-catenin proteins." (PMID 36523489, 2022). "In addition, we also found significant differences between SRSF1 IRS values, the patient’s gender, the tumor anatomic site, and histological subtypes; higher and lower SRSF1 levels were exhibited by superficial and nodular BCCs, respectively." (PMID 35056447, 2022). "Additionally, the knockout of SRSF1 in mouse models resulted in the inhibition of tumor cell migration." (PMID 35711821, 2022). "In mechanism, LINC01296 plays a tumor-promoting role by binding to SRSF1 protein." (PMID 34195277, 2021). "SRSF1 expression was consistently upregulated in BRCA samples, positively associated with tumor grade and the Ki-67 index, and correlated with poor prognosis in a hormone receptor-positive (HR+) cohort, which facilitated proliferation, cell migration and inhibited apoptosis in vitro and in vivo." (PMID 33992102, 2021). "miR-505-3p impedes neural tumor proliferation driven by SRSF1, solely in serum-reduced condition." (PMID 33718173, 2021). "Importantly, SRSF1 is a direct target of the proto-oncogene c-Myc and SRSF1 overexpression promotes tumor formation in mice." (PMID 33918758, 2021).
tumor (continued). "In addition, the immunohistochemistry (IHC) staining revealed that ESCC tumor tissues of interfering DGCR5 group had lower expression of SRSF1 and Mcl-1 protein." (PMID 34099633, 2021). "Our previous research has demonstrated that SRSF1 could mediate the aberrant AS of bridging integrator-1 (BIN1) to neutralize its tumor-suppressing functions in NSCLC23." (PMID 34099633, 2021). "Additionally, the mRNA expression level of SRSF1 was positively correlated with the mRNA expression of Ki-67 (R = 0.5, P < 0.05) and the tumor grade (P = 3.467e-08)." (PMID 33992102, 2021). "Both DBF4B full-length (DBF4B-FL) variant and SRSF1 promote tumor cell proliferation and tumor growth while the DBF4B-short (DBF4B-S) variant does not exhibit a similar function." (PMID 34330892, 2021). "We analyzed VEGF isoforms, Wt1, Srpk1, and Srsf1 in normal and tumor endothelium." (PMID 30641926, 2019). "Inhibition of Srpk1 and Srsf1, and alterations in Vegf splicing, which induce tumor endothelial cell apoptosis, might contribute to the antitumor activity upon targeting Wt1." (PMID 30641926, 2019). "Therefore, we determined VEGF isoforms, Wt1, Srpk1, and Srsf1 expression in normal and tumor endothelial cells." (PMID 30641926, 2019). "Hence, the increased expression of HABP1 and SRSF1 in HepR21 cells, their co-localization and the nuclear localization of SRSF1 might have a role in the generation of alternatively spliced variants of certain genes and increased tumor potency in this cell line." (PMID 29535843, 2018). "SRSF1 knockdown completely suppressed the tumor growth in both SCLC models." (PMID 27093186, 2016). "However, other researchers have demonstrated that some drugs that block tumor growth and induce cell cycle arrest promote production of pro-apoptotic MCL-1S and BCL-XS variants through downregulation of the AS/SF2 (SRSF1) splice factor." (PMID 27613060, 2016). "With these factors in mind, we propose that SRSF1 may also rely on modulating H2AX signal to sustain the tumorigenicity in some SCLC tumor patients." (PMID 27093186, 2016). "We next evaluated SRSF1 as a potential tumor driver in SCLC." (PMID 27093186, 2016). "Thus, downregulation of MNK2a due to SRSF1 activity controlled by SRSF1 constitutes a tumor suppressor mechanism that is lost in tumors such as breast, lung, and colon." (PMID 26273588, 2015). "In addition, we discover and experimentally validate PPIs between the oncoprotein SRSF1 and members of the anti-tumor drug target SF3 complex." (PMID 26047612, 2015). "This suggests that the oncogenic function of SRSF1 could be partially due to its role in promoting the translation of factors that are involved in suppressing multipolar divisions in human tumor cells." (PMID 24842991, 2014). "In a recent review it was noted that SRSF1 has also been shown to promote tumor transformation and growth by several mechanisms; for example, by stabilizing mRNA of anti-apoptotic factors 21 and by generating inactive tumor suppressor proteins by alternative splicing." (PMID 25525413, 2014). "Several mechanisms were proposed as to how SRSF1 promotes tumour development." (PMID 23592547, 2013). "Furthermore, SRPK1, the protein kinase that promotes the entry of SRSF1 into the nucleus, is transcriptionally repressed by the Wilms tumour suppressor WT1." (PMID 24101931, 2013). "Furthermore, combined RBM15 and SRSF1 knockdown further inhibited tumor growth." (PMID 40923717, 2026). "Finally, we verified that RBM15 promoted tumor growth by mediating SRSF1 in vivo." (PMID 40923717, 2026). "These variations imply that tumor intrinsic SRSF1 may also influence the T-cell compartment." (PMID 39837814, 2025). "Additionally, SRSF1 may influence the function of tumor-infiltrating T cells by regulating the splicing of genes related to immune suppression, thereby helping tumor cells evade immune surveillance." (PMID 39497723, 2024).
tumor (continued). "The aim of the present study was to evaluate the potential association between the immunohistochemical expression of SRSF1 and the risk of the local recurrence of a series of 52 surgically excised BCCs with histological tumor-free margins (47 non-recurrent versus 5 recurrent tumors)." (PMID 35056447, 2022). "In addition, in contrast to SRSF1, hnRNPA1 exclusively localized in tumor nuclei." (PMID 34065983, 2021). "Moreover, SRSF1 was more expressed in tumor tissues compared to their normal counterparts." (PMID 27999187, 2017). "In particular, we found recurrent deletions and insertions on the alternative exon in COAD and BRCA tumor samples that coincide with the presence of the switch, which fall on a region of low conservation that is next to a putative binding site for the splicing factor SRSF1." (PMID 25578962, 2015). "Thus, the overexpression of SRSF1 could lead to a change in alternative splicing of several pre-mRNAs that, together, result in a phenotype that gives the tumour a growth advantage." (PMID 24101931, 2013). "In short, RBM15‐mediated m6A modification enhanced SRSF1 stability, and SRSF1 promoted ATP7B alternative splicing to inhibit cuproptosis, thereby promoting NSCLC cell proliferation and tumor growth." (PMID 40923717, 2026). "Overexpression of SRPK1/2 in colon adenocarcinoma (CAC) enhances SRSF1 phosphorylation, which subsequently leads to MKNK2 AS into MKNK2b, ultimately promoting tumor growth." (PMID 39885614, 2025). "For example, the E3 ubiquitin ligase, RNF125, was dramatically downregulated in HCC tumor tissues, and experimental results indicate that RNF125 interacts with SRSF1." (PMID 40129567, 2025). "Our in vivo data revealed that Srsf1 knockdown had a combinatory effect with anti-PD1 against tumor growth in Hepa1-6 and B16F10 subcutaneous tumor models." (PMID 39837814, 2025). "We conducted RNA sequencing on SRSF1-sh and control Hep1-6-OVA tumor cells to examine the impact of SRSF1-sh on glycolytic metabolism." (PMID 39837814, 2025). "EBNA1 condensate interacting molecules are examined and are found that EBNA1 interacts with the splicing factor SRSF1 to regulate alternative splicing of SRRM1 and promote tumor progression." (PMID 40729735, 2025). "Further analysis of TCGA LUAD cohort data revealed that the expression levels of SRPK1, SRSF1, and RBM39 significantly upregulated in tumor compared to adjacent non‐tumor tissues, and positively correlated with RAC1B levels." (PMID 40548642, 2025). "Together, these results suggested that cells in node I were capable of hijacking the expression of multiple splicing factors, such as SRSF1 and SF1, apparently leading to dysfunctional gene splicing related to prosurvival pathways and tumor progression." (PMID 37308475, 2023). "As an example, MKNK2, a SRSF1 target, activates the p38-MAPK stress response pathway, a tumor suppressive pathway." (PMID 37510283, 2023). "Specifically, the splicing machinery components KHDRBS1, NOVA1, PRPF8, SNW1, SRSF1, SRSF10 and SRSF9 were overexpressed in tumor tissue." (PMID 38049848, 2023). "Restoration of circ_000829 reduced the levels of SRSF1 and SLC39A14B, thereby repressing the RCC cell proliferation in vitro and tumor growth in vivo." (PMID 36062189, 2022). "Meanwhile, RT-qPCR results displayed that the expression of SRSF1 mRNA and SLC39A14B mRNA was downregulated, while the expression of SLC39A14A mRNA was increased in tumor tissues of mice following circ_000829 overexpression." (PMID 36062189, 2022). "Bin1+12a isoform was determined to abolish its tumor suppressor role in NSCLC and is promoted by SRSF1 overexpression." (PMID 35463320, 2022). "Then, the effects of circ_000829, SRSF1, and SLC39A14 on cell cycle distribution and proliferation in vitro and on tumor growth in vivo were evaluated in RCC cells." (PMID 36062189, 2022).
tumor (continued). "Further functional assays confirmed that knockdown of SRSF1 suppresses proliferation, cell migration, promotes cell cycle arrest and apoptosis in BRCA cells in vitro, and inhibits tumor growth in vivo." (PMID 33992102, 2021). "In vivo experiments further validated that lnc-KASRT enhanced tumor growth and reduced tumor apoptosis; meanwhile, it also increased tumor KLF6-SV1, MMP-1, and MMP-9 expressions but decreased tumor SRSF1 and KLF6-WT expressions in xenograft mice." (PMID 34568030, 2021). "In contrast, tumor volumes were increased in the HOXB5 overexpression group, the SRSF1 overexpression group, the circATP5B knockdown combined with the HOXB5 overexpression group, and the miR-185-5p mimic combined with the HOXB5 overexpression group." (PMID 33858489, 2021). "SRSF1-mediated AS regulation generates protein isoforms promoting cell migration and EMT, which have pro-oncogenic capabilities or lack tumor suppressor activity, and influence angiogenesis." (PMID 33918758, 2021). "USP39 acted as a pro-tumor factor by motivating the malignant biological processes of RCC, probably through inhibiting VEGF-A165b alternative splicing and regulating SRSF1 and SRPK1." (PMID 34544400, 2021). "High nucleus SRSF1 promoted MKNK2 splicing into MKNK2b instead of MNK2a, consequently enhanced tumor proliferation." (PMID 33602301, 2021). "Meanwhile, within the SRSF1 intronic region, UCR-419 (named lnc-KASRT) fits the definition of a lncRNA and regulates KLF6 (a common tumor regulator) alternative splicing by sponging the SRSF1 gene." (PMID 34568030, 2021). "Knockout of WT1 in tumor endothelium decreased SRPK1 and SRSF1 expression and shifted VEGFA splicing toward the production of the anti-angiogenic VEGF-A120 isoform." (PMID 33287867, 2020). "We observed DHX9 and MATR3 (in Tumor A, set 1), HNRNPC and LARP1 (in Tumor A, set 2), SRSF1 (in Tumor B, set 1 & Tumor B, set 2), SRSF6 and IGF2BP2 (Tumor B, set 2), HNRNPU (in Tumor B, set 2 & Tumor C, set 2), and FAM120A and HNRNPA2B1 (in Tumor C, set 2)." (PMID 31892958, 2020). "We have identified SF2, the Drosophila homolog of human SRSF1, as an Achilles heel of pre-tumorous cells devoid of the tumor suppressors Pten or Tsc1, which rely on TORC1 activity to grow and proliferate." (PMID 32599686, 2020). "In conclusion, Wt1 activates Srpk1 and Srsf1 and induces expression of angiogenic VEGF isoforms in tumor endothelium." (PMID 30641926, 2019). "For example, the splicing factor SRSF1 is found to act as a proto-oncogene to promote cell transformation, whereas the splicing suppressor RBM4 functions as a tumor suppressor to inhibit tumor progression." (PMID 25749525, 2015). "BIN1 has tumor-suppressor activity by interacting with and activating MYC-mediated apoptosis, except when exon 12A is included by SRSF1-mediated alternative splicing, because the resulting antiapoptotic BIN1+12A isoform is unable to interact with MYC." (PMID 26273603, 2015). "We further demonstrate that, like SRSF1, SRSF9 is also an oncogene, and is frequently overexpressed in multiple types of human tumours." (PMID 23592547, 2013). "Both SRSF1- and SRSF9-overexpressing cells were tumorigenic and the SRSF9-induced tumours seemed even larger than those of SRSF1." (PMID 23592547, 2013). "Increased SRSF1 gene expression can transform rodent fibroblasts in an NIH3T3 assay, and the resulting transformed cells form tumours in nude mice." (PMID 23935626, 2013). "The impact of reduced tumor-intrinsic SRSF1 expression on T cell-mediated antitumor activity is not yet understood." (PMID 39837814, 2025).